MBD4 (methyl-CpG binding domain 4, DNA glycosylase)
Diseases named in the same sentence as MBD4 in open-access papers (continued):
Sharing a sentence is not in itself a finding about the gene and the disease.
tumor (continued). "Tumor burden at time of death was significantly greater in Mbd4−/− versus the WT mice, measured both as number of polyps per colon and by the ratio of tumor to non-tumor area in the colonic lumen." (PMID 27086921, 2016). "Mbd4−/− mice also showed trends towards increased scores for crypt atrophy, hyperplasia and extent of neoplasia." (PMID 27086921, 2016). "Here, we show that Mbd4−/− mice exhibit greater morbidity and mortality in response to colonic inflammation and that this is accompanied by increased tumor burden versus WT controls." (PMID 27086921, 2016). "Mbd4−/− mice have shorter survival times than wild-type (WT) mice with a greater tumor burden at time of death, and more severe clinical symptoms throughout the study." (PMID 27086921, 2016). "Inflammation and stage of neoplasm were very modestly but significantly decreased in Mbd4−/− relative to WT colons." (PMID 27086921, 2016). "Taken together, the more severe clinical symptoms, reduced survival, and greater tumor burden in AOM/DSS treated Mbd4−/− versus WT mice suggest that the Mbd4 protein plays a role in suppressing inflammation-driven colon carcinogenesis." (PMID 27086921, 2016). "In the AOM/DSS assay, Mbd4−/− mice displayed more severe clinical symptoms, decreased survival, and a greater tumor burden than wild-type (WT) controls." (PMID 27086921, 2016). "In keeping with the survival differential, a difference in tumor incidence and distribution was observed in Mbd4−/−Mlh1−/− double knock-out mice compared with Mlh1 single knockout mice." (PMID 26503472, 2015). "Regarding tumor prognosis, reduced expression of MBD4 correlated with poorly differentiated tumors in hepatocarcinomas (HCC)." (PMID 24212783, 2011). "The important difference between the mouse studies and this is that the effects presented here occurred owing to expression of a naturally occurring truncation mutant of MBD4 found in authentic human tumours." (PMID 17285135, 2007). "Future studies may reveal whether the mechanism of tumor suppression by MBD4 is through addressing spontaneous deamination of 5mC or through a more complex system involving AID/APOBEC enzymes." (PMID 36618446, 2021). "Immunotherapy, which is helpful in UMs with a MBD4 mutation and a high mutation burden, is therefore probably also useful for iris melanomas, but luckily, these tumours do not often give rise to metastases." (PMID 32998469, 2020). "If only the difference in tumor burdens between the two genotypes within each experiment is considered, this result would appear to support the conclusion that replacement of Mbd4−/− hematopoietic cells with WT reduces the tumor burden in AOM/DSS treated Mbd4−/− mice to WT levels." (PMID 27086921, 2016). "Truncated MBD4 was expressed in MBD4-mutant tumour cells albeit at an apparently lower level." (PMID 17285135, 2007). "Mutation of MBD4 (normal function being the repair of methyl-CpG deamination events) occurs in microsatellite unstable tumours and absence of the gene in MBD4 null mice leads to increased genomic mutations and tumour burden in APCmin mice." (PMID 15138480, 2004). "It is thus not entirely clear whether the lack of difference in tumor burden between genotypes in the transplanted mice is due to a rescue of the cancer prone Mbd4−/− phenotype, and the similar tumor burden in both genotypes may relate to the radiation exposure used to ablate endogenous BM." (PMID 27086921, 2016). "Moreover, a binomial test of proportions between the frequency of MBD4 pathogenic and likely non-pathogenic variants in tumor and control samples was also significant (p-value < 0.0001)." (PMID 26503472, 2015). "Absence of Mbd4 in mice also increases tumorigenicity in the tumour-susceptible APCmin background." (PMID 17285135, 2007).
tumor (continued). "Unique molecular characteristics have been described in neoplasms from defective DNA repair-related polyposis involving the MUTYH, NTHL1, MBD4, MSH3, POLE and POLD1 genes and the MMR genes in CMMRD." (PMID 40237887, 2025). "The expression levels of three writers (DNMT1, DNMT3A, DNMT3B), two erasers (TET1, TET3), and eight readers (MBD4, ZBTB33, UHRF1, UHRF2, UNG, TDG, NTHL1, SMUG1) were dramatically higher in tumor tissues (p < 0.05)." (PMID 38317133, 2024). "Despite the recapitulation of the more severe clinical symptoms in transplanted Mbd4−/− mice in the AOM/DSS assay, transplanted WT and transplanted Mbd4−/− mice had similar tumor burdens at the time of death." (PMID 27086921, 2016). "In addition, when Mbd4 mutant mice were crossed into mice mutant for the tumor suppressor gene Apc or the MMR gene Mlh1, an increased tumor burden and rate of tumor progression is noted." (PMID 36618446, 2021). "Despite not differing in tumor burden at time of death, the transplanted Mbd4−/− mice nevertheless had drastically reduced survival time and drastically increased clinical morbidity as measured by weight loss." (PMID 27086921, 2016). "Taken together, these results suggest that the greater tumor burden in AOM/DSS treated Mbd4−/− mice is not due to increased tumor initiation by AOM." (PMID 27086921, 2016). "The increased tumor burden in Mbd4−/− mice did not arise from impairment of AOM-induced apoptosis in the intestinal crypt." (PMID 27086921, 2016). "Selected CRC target genes involved in apoptosis (BAX), tumor growth (TGFβRII), WNT pathway (AXIN2, TCF4, WISP3), DNA repair (ATM, ATR, BLM, BRCA1, BRCA2, DNAPKcs, MBD4, MRE11, MSH3, MSH6, RAD50, XRCC2) and PI3-kinase signaling (PTEN) were analyzed for mutations in MSI-positive HGG samples." (PMID 21637783, 2011). "This also suggests that MutSα-mutated tumours display the unrepaired and potentially complete spontaneous deamination rate of 5-methylcytosine and that the MMR machinery plays a pivotal role in the repair at these sites, potentially guided by MBD4 for strand-discrimination in non-replicating dsDNA." (PMID 39026103, 2024). "Thus, MBD4 inactivation may not be sufficient to initiate tumorigenesis but may play a significant role in tumor progression." (PMID 29760383, 2018). "Transplantation of WT bone marrow into Mbd4−/− mice does not affect the decreased survival time or the intensified colonic injury induced by AOM/DSS; however, the tumor burden at death was similar between transplanted Mbd4−/− and WT mice." (PMID 27086921, 2016).
cancer (26 papers, 2007 to 2025). A tumor composed of atypical neoplastic, often pleomorphic cells that invade other tissues. "Detecting heterozygous PVs in the MUTYH, NTHL1, MSH3, and MBD4 genes poses a clinical challenge for counseling monoallelic carriers about their cancer risk and for establishing rational surveillance protocols." (PMID 40237887, 2025). "None of the patients displayed pathogenic or likely pathogenic variants in the BAP1 and MBD4 genes or in other well-established cancer-predisposing genes." (PMID 38892746, 2024). "MBD4 is responsible for the repair of C > T deamination mutations at CpG dinucleotides and has been linked to somatic hypermutation and cancer predisposition in humans." (PMID 37984997, 2023). "Having demonstrated in vitro the high sensitivity of MBD4 deficiency cancer cell lines to cytidine analogs, we then studied their effect in a co-clinical model." (PMID 36323843, 2022). "In summary, MBD4 deficiency increased the sensitivity of cancer cell lines to cytidine analogs (gemcitabine and cytarabine), but not to other classes of chemotherapeutic agents, including dacarbazine, commonly used in UM treatment." (PMID 36323843, 2022). "Analysis of previously published whole-exome sequencing samples from the TCGA (n = 8,134) replicated the association between germline MBD4 PTVs and increased somatic CpG mutagenesis at the pan-cancer level (P = 7.1 × 10−4)." (PMID 32025007, 2020). "DNA repair capacity and cancer incidence were associated with MBD4 polymorphisms and frameshift mutations." (PMID 32547565, 2020). "Recently-reported exceptional immune responses in UM patients harboring MBD4 mutations point up the importance of deciphering cancer mechanisms in order to determine the oncogenic actors and develop the appropriate therapeutic strategies." (PMID 31330784, 2019). "In humans, sequence alterations in MBD4 and altered MBD4 expression are associated with elevated cancer risk." (PMID 27086921, 2016). "Mbd4−/− mice were previously shown to have no change in the rate of spontaneous tumorigenesis versus WT mice, although loss of Mbd4 did accelerate tumorigenesis in the ApcMin/+ cancer-prone model." (PMID 27086921, 2016). "Despite the extensive associations between the MBD4 DNA glycosylase and human cancer, the specific context in which MBD4 is important for suppressing tumors has remained unclear." (PMID 27086921, 2016). "Here, we evaluated the contribution of Mbd4 inactivation on an Mlh1-cancer predisposing background in vivo." (PMID 26503472, 2015). "On a MMR defective background MBD4 mutation (due to polyadenine tract alterations) occurs frequently in human cancers leading to premature truncation of the MBD4 protein, which lacks the whole glycosylase domain." (PMID 24212783, 2011). "Good responses have also been observed in MUTYH- and MBD4-deficient cancers." (PMID 40237887, 2025). "SBS1 is associated with spontaneous deamination of 5-methylcytosine (5mC), resulting in C > T substitutions, and we have recently associated SBS1 with base-excision repair and MBD4-deficiency in pan-cancer studies (The ICGC/TCGA Pan-Cancer Analysis of Whole Genomes Consortium, 2020)." (PMID 39026103, 2024). "It was also shown that the sensitivity of some cancer cell lines to gemcitabine and another cytidine analog, cytarabine, was increased by the deficiency of MBD4 gene, which encodes methyl-CpG binding domain 4 (MBD4)." (PMID 39189649, 2024). "Additionally, many types of cancerous tumors are often found to contain mutations in the MBD4 gene, especially gastric, endometrial, and pancreatic carcinomas." (PMID 37984997, 2023). "Similarly, a dramatic increase in the rate of CpG>TpG mutations is observed when MBD4 is inactivated in cancer cells." (PMID 36323843, 2022). "We can also hypothesize that our results may have consequences beyond MBD4 deficiency, on the treatment of cancers that are proficient for MBD4." (PMID 36323843, 2022).
cancer (continued). "MBD4, a DNA repair gene that deals with mismatches within methylated CpG sites, showed rare germline PTVs with an expected increased rate of somatic C to T mutations at the pan-cancer level." (PMID 34097189, 2021). "MBD4 has been implicated in the onset and occurrence of cancer." (PMID 32547565, 2020). "Thus, the role of MBD4 in MMR-deficient tumorigenesis, which is precisely the situation in which most MBD4 mutations in human cancer occur, is still a matter under debate." (PMID 26503472, 2015). "The naturally occurring MBD4 truncation at amino acid 313 in MMR‐deficient human carcinomas presumably has the potential to affect the protein interaction profile of MBD4 in addition to losing the catalytically active C‐terminal glycosylase domain (black arrow)." (PMID 25358258, 2015). "A role for MBD4 germline mutations in cancer predisposition was hypothesized 18 years ago13." (PMID 29760383, 2018). "In addition to its role in base excision repair, Mbd4 has been implicated in several other processes that may influence the development of cancer." (PMID 27086921, 2016). "However, we and others have found an association of truncating mutations of MBD4 in human MSI cancers, especially colon, and in most cases these mutations occur in the presence of a remaining intact MBD4 allele, that is, the null genotype is not seen naturally." (PMID 17285135, 2007). "After a large-scale drug repurposing screen, we show in two isogenic MBD4 knock-out cell models that the inactivation of MBD4 sensitizes cancer cells to cytidine analogs." (PMID 36323843, 2022). "In humans, a naturally occurring frameshift mutation of a polynucleotide tract in MBD4 has been found in microsatellite unstable (MSI) colon and other cancers that leads to a premature stop in translation of the mRNA." (PMID 17285135, 2007). "Taken together these studies support a tumor suppressive function of MBD4 in cancer even though more research is needed to elucidate whether this effect is common for all cancer or specific for certain types of cancer." (PMID 31245293, 2019). "Taken together, these data suggest that MBD4 inactivation may contribute to tumorigenesis, acting as a modifier of MMR-deficient cancer phenotype." (PMID 26503472, 2015). "Noteworthy, our findings differ from a previous study, in which biallelic inactivation of Mbd4 had no impact on mutation frequency in vivo and did not modify the cancer predisposition phenotype in mice doubly deficient for Mbd4 and MMR genes." (PMID 26503472, 2015). "In vitro studies have shown that loss of the mbd4 gene does not result in tumorigenesis; however, it results in the formation of a pool of C and T at CpG sites which may result in the predisposition to cancer." (PMID 39189649, 2024). "As for the explants, MBD4 and LIG1 had higher expression in obese patients compared to lean participants and cancer patients (p < 0.05)." (PMID 36982562, 2023). "Among epigenetic genes, DNA methylation related epigenetic modifiers, DNMT1, DNMT3A, MBD1, MBD4, TET1, TET2, and TET3, have been studied related to cancer." (PMID 32093698, 2020). "In this paper, we investigated the effect of mutations on DNA methylation modification genes such as DNMT1, DNMT3A, MBD1, MBD4, TET1, TET2, and TET3 through a pan-cancer analysis." (PMID 32093698, 2020). "Therefore, we investigated the effect of mutations on DNA methylation modification genes such as DNMT1, DNMT3A, MBD1, MBD4, TET1, TET2 and TET3 through a pan-cancer analysis." (PMID 32093698, 2020).
cancer (continued). "In addition, in the absence of MBD4, C to T transitions at CpG sites will be generated which would lead to genome instability, as determined in Mbd4−/− mice and several human cancers." (PMID 37957685, 2023).
infection (3 papers, 2016 to 2024). The state of being infected such as from the introduction of a foreign agent such as serum, vaccine, antigenic substance or organism. "In experimental tuberculosis, expression of mBD3 and mBD4 by airway epithelial cells in the early stages of infection correlated with temporary control of mycobacterial growth." (PMID 27725944, 2016). "After 1, 3 and 7 d of post-infection (PI), the samples needed for detecting of the mRNA levels of mouse beta-defensin (mBD)-1, mBD2, mBD3, mBD4, mBD6, cathlin-related antimicrobial peptide (CRAMP), interleukin (IL)-10, IL-12 and parasite load were taken under standard methods." (PMID 30697304, 2018). "Interestingly, more highly virulent M. bovis strains induce lower levels of murine β-defensin 4 (mBD4) expression than strains of lower virulence during many time points of early infection, indicating the ability to suppress induction early in infection in vivo." (PMID 27725944, 2016).
gastrointestinal tumors (1 paper, 2023). "Congruent with the function of MBD4, C > T mutations are found in high incidence in gastrointestinal tumors of MBD4−/− mice, with most occurring at CpG dinucleotides." (PMID 37984997, 2023).
psychiatric disease (1 paper, 2015). "Expression of MBD4 developmentally regulates several tissues, and its aberrant expression in hippocampal GABAergic neurons in psychiatric disease may be linked to abnormal differentiation in these cells." (PMID 26322075, 2015).
MBD4 also shares sentences with these, for which no sentence is quoted: adenocarcinoma (1 paper); age-related macular degeneration (1); astrocytoma (1); bipolar disorder (1); brain tumors (1); cervical cancer (1); diabetes (1); diabetes retinopathy (1); Encephalopathy (1); endometrial adenocarcinomas (1); endometrial cancer (1); gestational diabetes (1); head and neck squamous cell carcinoma (1); hereditary colorectal cancer (1); hypertrophic cardiomyopathy (1); juvenile polyposis syndrome (1); lung carcinoma (1); mutyh-associated polyposis (1); Myelodysplasia (1); nephrogenic diabetes insipidus (1); neurodegenerative disease (1); peptic ulcer disease (1); Peutz-Jeghers syndrome (1); prostatic hyperplasia (1); PTEN hamartoma tumor syndrome (1); Rett syndrome (1); rheumatoid arthritis (1); sarcoma (1); schwannoma (1); Sézary syndrome (1).
A further 4 diseases each share a sentence with MBD4 in 1 paper.